GSTP1 (glutathione S-transferase pi 1)
Diseases named in the same sentence as GSTP1 in open-access papers (continued):
Sharing a sentence is not in itself a finding about the gene and the disease.
tumor (299 papers, 1998 to 2026). "Methylation patterns of GSTP1 in tumor tissues displayed a significant association with the Gleason stage." (PMID 39783747, 2025). "This variant was the lead eQTL for one of two credible sets of GSTP1, a tumour suppressor gene for which its expression has been implicated in breast cancer." (PMID 39020179, 2024). "The high specificity of GSTP1 promoter methylation to tumour tissue makes it an ideal diagnostic biomarker." (PMID 39744075, 2024). "This assay is based on epigenetic changes associated with the risk of PC development existing/occurring adjacent to tumor foci (halo effect) and evaluates quantitatively the DNA methylation level of GSTP1, APC, and RASSF1." (PMID 38254807, 2024). "GSTP1 is well‐characterised as a detoxifying enzyme and tumour suppressor, and aberrant methylation of the GSTP1 promoter has been associated with tumour development and prognosis in a range of tumour types." (PMID 39744075, 2024). "This variant is the lead eQTL for one of two credible causal sets of gene GSTP1, a tumor suppressor gene whose expression has been implicated in breast cancer." (PMID 37965206, 2023). "This shows that overexpression of GSTP1 protein in tumor cells and its nuclear localization are closely associated with more advanced tumor staging and worse prognosis." (PMID 36589232, 2022). "According to our results, the presence of a high level of GSTP1 in a tumor biopsy is associated with the low efficiency of the NAC CP scheme (p = 0.05)." (PMID 35204496, 2022). "A recent study showed that high expression of GSTP1 can activate the NF-κB signaling pathway in tumor associated macrophages (TAMs) and regulates the expression of IL-669." (PMID 35027621, 2022). "By in situ hybridization, GSTP1 mRNA expression was concordant with protein staining, supporting the lack of silencing of at least some GSTP1 alleles in GSTP1-positive tumor cells." (PMID 34191807, 2021). "The presence of the GSTM1 null genotype is associated with increased risk for HNSCC, while the GSTT1 null genotype and the A313G GSTP1 polymorphism contribute to decreased risk for this tumor type." (PMID 32592358, 2020). "Hypermethylation of GSTP1 in the promoter region, which encodes glutathione S-transferase P1, was found in about 50% of tumor tissues, including HCC." (PMID 31546948, 2019). "On the other hand, it was reported that loss of GSTP1 expression enhances cell susceptibility to acquire additional alterations and undergo further genetic changes toward tumor progression (Schnekenburger, Karius, & Diederich, 2014)." (PMID 30043549, 2018). "Chi-square and Fisher's exact tests showed that tumor size (P=0.023) and clinical stage (P=0.049) were significantly associated with GSTP1 expression." (PMID 28978147, 2017). "The results of our study showed that patients with the GSTP1 AA genotype had a significantly reduced risk of tumor recurrence after receiving epirubicin." (PMID 26354850, 2015). "GSTP1 encodes glutathione S-transferase, a tumor suppressing enzyme involved in drug metabolism and detoxification, working to protect DNA from oxidative damage." (PMID 25238417, 2014). "In particular, the association of GSTP1 Ile105Val genetic polymorphisms with tumor aggressiveness and response to cyclophosphamide (CTX) and CTX-based chemotherapy remains unidentified." (PMID 23826324, 2013). "GSTP1 promoter hypermethylation was detected in one-third of tumor biopsies (74/215) and was found to be associated with a loss of expression." (PMID 23226781, 2012). "Even the tumor epithelium and tumor-associated stroma have shown different methylation profiles, as GSTP1 and RARbeta2 were found to be hypermethylated in the tumor epithelium and less so in tumor-associated stroma." (PMID 21625442, 2011).
tumor (continued). "By comparing responses of mGstp1/2+/+ and Gstp1/2−/− mice to chemical carcinogens, π-class GSTs have been implicated in protection against tumor development in several different organ sites, including the skin, the colon, and the lungs." (PMID 22022436, 2011). "Some of these epigenetic changes, notably hypermethylation of genes like GSTP1, appear to be associated with earlier stages of tumor development, whereas others are rather associated with tumor progression." (PMID 24213107, 2011). "For GSTP1, all samples demonstrated methylation in both the tumor-associated endothelium and tumor epithelium." (PMID 16512911, 2006). "Studying eight prostate cases, we demonstrate that indeed methylation of GSTP1 and RARβ2 in tumor-associated endothelium was similar to that of microdissected tumor epithelium." (PMID 16512911, 2006). "Subsequently, we identified, via bisulfite modification and QMS-PCR analysis, promoter methylation changes between tumor-associated endothelium and normal endothelium for GSTP1 and RARβ2." (PMID 16512911, 2006). "If GSTP1 hypermethylation is associated with the onset of prostate carcinogenesis, it cannot be related to tumour stage or Gleason score, as observed here and by others." (PMID 15292941, 2004). "For instance, while polymorphic variants in the GSTP1 gene have been associated with the metabolism of pesticides and with the development of neoplasms, polymorphisms in the XRCC1 gene have been linked to an elevated risk of DNA damage caused by pesticide exposure." (PMID 38673753, 2024). "The expression of GSTP1 is observed in various tissues and is associated with the metabolism of diverse carcinogenic compounds, protection against DNA damage, and activation of tumour suppressor genes." (PMID 38890797, 2024). "The GSTP1 rs1695 (c.313A > G, Ile105Val) polymorphism may influence GSTP1 enzyme activity, which is linked to chemotherapy drug detoxification and tumor cell sensitivity." (PMID 35729577, 2022). "Moreover, expression and overexpression of GSTP1 are common in several human tumor types, where it has been implicated in promoting resistance to a number of chemotherapeutic agents." (PMID 34191807, 2021). "The observed effects may be influenced by high susceptibility of minute amounts of methylated GSTP1 tumour DNA fragments to deoxyribonuclease (DNase) degradation in blood stream/serum." (PMID 34503269, 2021). "It is important to note that polymorphisms in GSTP1 and other GSTs could also contribute to PC occurrence and progression, affecting both the proliferation capacity of tumor cells and their response to therapy." (PMID 32183092, 2020). "Furthermore, promoter methylation of both CDKN2A (p14ARF) and MGMT has been associated with tumour stage and the addition of GSTP1 and TIMP3 promoter methylation allowed to discriminate invasive tumours." (PMID 30149597, 2018). "Odds ratios (ORs) and 95% confidence intervals (95% CIs) were calculated for the association of GSTP1 polymorphism with tumour response and toxicities, and the hazard ratios (HRs) and 95% CIs were calculated for the association between GSTP1 polymorphism and overall survival (OS)." (PMID 29069838, 2017). "In addition, eight studies comprising 832 patients were pooled for the OR in evaluating the association between GSTP1 methylation and tumor stage." (PMID 26585467, 2015). "Interestingly, some of these genes have been previously associated with CIMP in other tumor types, such as p73, GSTP1, SOCS-1, CACNA1G, CRABP1, NEUROG1 and RUNX3." (PMID 20830311, 2010). "Therefore, the expression and function of DPYD, TYMS, MTHFR, ERCC1, ERCC2, XRCC1, and GSTP1 may be influenced not only by genetic polymorphisms, but also by processes that are specific for the tumor tissue." (PMID 33429840, 2021).
tumor (continued). "Furthermore, to confirm the tumor-origin of the PDCOs we have analyzed the expression of PC-associated epigenetic biomarkers including promoter methylation of the GSTP1, RASSF1 and APC and RARb genes by employing a novel microfluidic rare-event screening protocol." (PMID 34581895, 2021). "Since the DNA was extracted from areas with >90% cancerous tissue, comprising both tumor-epithelial and tumor-associated stromal cells, we have semi-quantified the stroma content of the tissues from the PCa2 cohort and analysed the correlation with GSTP1 DNA methylation." (PMID 26086362, 2015). "For instance, LAS17, one of the most effective known inhibitors, has an IC50 of 500 nM and works by covalently binding to tyrosine residues on GSTP1, showing significant efficacy in reducing tumor growth in xenograft models with minimal toxicity." (PMID 39954068, 2025). "This interpretation is supported by induction of host stress- and remodeling-related genes (Ddit3, Gstp1, Spon2), representing a molecular signature of tissue repair and immune infiltration consistent with the observed tumor regression." (PMID 41463401, 2025). "These agents work by inhibiting the DNA methyltransferases responsible for adding methyl groups to the promoter regions of genes, thus restoring the expression of silenced genes, including tumor suppressors like GSTP1." (PMID 40051701, 2025). "A parallel correlation was established between hypermethylation of GSTP1 and tumor stage (p = 0.00004)." (PMID 39783747, 2025). "This suggests their potential utility as anti-tumor agents, particularly against tumors with elevated GSTP1 expression." (PMID 40290119, 2025). "In the context of epigenetic alterations, DNA hypermethylation of tumor suppressor genes (e.g., GSTP1, RASSF1A, and SOCS1), have been widely reported in HCC tissues and are associated with more aggressive tumor behavior and lower survival rates." (PMID 40601653, 2025). "The process of DNA methylation, particularly in the context of tumor suppressor genes like GSTP1, involves the addition of a methyl group to the cytosine residue of CpG islands in the promoter region." (PMID 40051701, 2025). "GSTP1 is a well-established tumor suppressor, and its upregulation leads to reduced PCa cell proliferation and increased apoptosis, effectively impeding disease progression." (PMID 40508012, 2025). "In our meta-analysis, we found a significant association between GSTP1 hypermethylation and poor clinical outcomes in HCC patients, including advanced tumor stage, recurrence, and reduced overall survival." (PMID 40051701, 2025). "SNHG14 and LINC00663 interact with EBF1 to enhance its protein stability and functional activity, whereas LINC00844 recruits EBF1 to the GSTP1 promoter to promote its transcription and exert anti-tumor effects." (PMID 40508012, 2025). "The methylation of genes such as RUNX3, GSTP1, SHOX2, DKK3, and MLH1 is associated with tumor progression and malignancy, with RUNX3 showing high promoter methylation in NSCLC tissues." (PMID 40136480, 2025). "Inhibiting GSTP1 activity has the potential to amplify chemotherapy’s cytotoxic effects by reducing drug detoxification and increasing oxidative stress in tumor cells." (PMID 39954068, 2025). "Because of GSTP1’s role in drug resistance and tumor survival, targeting this enzyme has become a promising therapeutic approach." (PMID 39954068, 2025). "Correspondingly, the serum exosome levels of GSTP1 were also substantially greater in the PD/SD cohort than in the PR/CR cohort, indicating a potential role for exosomal GSTP1 in modulating tumor responsiveness to chemotherapeutic agents." (PMID 39403606, 2024). "In summary, LF6 appears to reflect both impaired detoxification due to GSTP1 loss and altered immune regulation via INFG, creating a permissive environment for tumour progression." (PMID 39592856, 2024).
tumor (continued). "Surprisingly, we also found high expression levels of lipid metabolism genes in the B16F10 tumor cell subpopulation, including Gsta4, Gsta2, Gstp1, and Enpp2." (PMID 38755254, 2024). "In PCa, GSTP1 is methylated in its promoter region, leading to the diminished expression of GSTP1 in tumor cells." (PMID 38339274, 2024). "Consistent with this we found that in the GSTP1 head‐loop patient cohort (n = 185), 97% of tumour samples had detectable levels of mGSTP1 as measured by MS‐HL GSTP1 assay." (PMID 39744075, 2024). "GSTP1‐KD significantly reduced tumor growth rate and volume, whereas GSTP1‐OE promoted tumor formation." (PMID 36709476, 2023). "Overexpression of GSTs, particularly GSTP1-1 is often considered as a possible mechanism of tumor cell drug resistance." (PMID 37189435, 2023). "We identified two new (Y249 and Y322) phosphorylation sites influenced by the tumor metabolic microenvironment lactic acid sensing by GSTP1, which frees up G6PD from a tripartite complex to facilitate the PPP oxidative branch." (PMID 37491277, 2023). "In vivo studies using xenograft models in nude mice showed that tumor growth inhibition or regression was positively corelated with GSTP1-1 expression levels in response to TLK286 treatment, and a mild bone marrow toxicity was observed as a side effect." (PMID 37189435, 2023). "In the spatial transcriptome, it is clear that BARD1 expression is overall low, while CTSB and GSTP1 are mainly expressed in the core region of the tumor." (PMID 37727789, 2023). "Taken together, these results suggest that GSTP1 plays a key role in tumor development by functioning as a novel lactate sensor." (PMID 37491277, 2023). "This study unveiled that GSTP1 is upregulated in lung CSCs and supports tumor self‐renewal, metastasis, and resistance to targeted tyrosine kinase inhibitors of LUAD both in vitro and in vivo." (PMID 36709476, 2023). "We observed a tumor suppressing activity by a GSTP1 enzyme inhibitor NBDHEX in animal models, presumably by blocking the function of GSTP1 as a lactic acid sensor that impacts the GSTP1-G6PD-SRC complex." (PMID 37491277, 2023). "Aberrant DNA methylation was assessed for four genes—p16 (CDKN2A), O6-methylgua-nine-DNA-methyltransferase (MGMT), glutathione S-transferase P1 (GSTP1), and death-associated protein kinase (DAP-kinase)—in both primary tumor and serum of 50 HNSCC patients." (PMID 35406495, 2022). "Previous studies have found that the expression of GSTP1 in tumor tissues is higher than that in normal tissues, which provides a good research entry point for us to study the potential role of GSTP1 in tumor radiotherapy through ferroptosis." (PMID 36589232, 2022). "The level was significantly negatively correlated with the activator of apoptosis-enforcing protein caspase-3, indicating that the high expression of GSTP1 inhibited the apoptosis signaling pathway, thereby inhibiting tumor apoptosis." (PMID 36589232, 2022). "In tumor-related studies, it has been found that the high expression of GSTP1 promotes the chemoresistance of various tumors." (PMID 36589232, 2022). "Targeting downregulation of GSTP1 expression under tumor radiotherapy would increase radiosensitivity of lung tumors and thus promoting radiation-induced ferroptosis." (PMID 36589232, 2022). "For example, in a xenograft tumor model, deletion of GSTP1 significantly decreased tumor size via blocking the mitogen-activated protein kinase (MAPK) signaling pathway." (PMID 35936694, 2022). "GSTP1 expression in tumor tissues correlated positively not only with GSH levels γ-GCS and GR activity, but also with GPX and SOD activity in TCC." (PMID 36589232, 2022). "GSTP1 is overexpressed in a number of tumor cell lines resistant to several anticancer drugs that confer a cytoprotective role." (PMID 32737955, 2022). "Next, we wanted to determine range of detection of GSTP1 in samples representative of the purity of DNA isolated from circulating tumor cells (CTCs)." (PMID 35272673, 2022).
tumor (continued). "GSTP1 is an enzyme that catalyzes the detoxification pathways of platinum drugs to protect cells, including tumor cells." (PMID 36294786, 2022). "We found spot 3303 with GSTP1 was upregulated in the central as well as the peripheral part of the tumor and by 1D-WB, GSTP1 was upregulated in the peripheral part." (PMID 34563043, 2021). "Spatial sampling of breast cancer cell populations revealed a divergent profile of DNA methylation across the tumour that is mainly detected at genes such as GSTP1, FOXC1, ABCB1, PTEN, and TGM2 that contribute to drug resistance." (PMID 34298745, 2021). "Increased expression of GSTP1 has been detected in most tumor tissues and is closely related to tumorigenesis and development." (PMID 33893729, 2021). "While some cases were uniformly positive for GSTP1, in other cases containing GSTP1 positive tumor cells, we often observed heterogeneity in staining in terms of both cell number and staining intensity." (PMID 34191807, 2021). "HCC recurrence following tumor resection was also detected up to 9 months before MRI diagnosis by monitoring GSTP1 and RASSF1A ctDNA methylation in the urine of patients." (PMID 33809263, 2021). "GSTP1 has been negatively correlated with tumor size and serum alpha-fetoprotein (AFP) in HCC patients while higher GSTP1 levels have been associated with longer overall survival and better prognosis." (PMID 33673113, 2021). "We also performed IHC and in situ hybridization for GSTP1 mRNA on a number of standard slides from prostatectomy specimens and found an example that was heterogeneous for GSTP1 protein in the tumor." (PMID 34191807, 2021). "Increased expression of Ccl5 promotes tumour proliferation and metastasis, high expression of Bcl2 inhibits apoptotic death, favouring neoplastic cells proliferation and Gstp1 is a marker of preneoplastic foci in liver tissue." (PMID 34650394, 2021). "For example, GSTP1 hypermethylation, one of the most common epigenetic events in PCa tumour specimens, has been readily detected in liquid biopsy samples from PCa patients, such as urine, semen, blood serum and plasma samples." (PMID 33076494, 2020). "In this study, the cytotoxicity of the most effective inhibitor of GSTP1-1 activity; T. indica n-butanol fraction, on the following human tumor cell lines: liver HePG 2; colon HCT116." (PMID 33215267, 2020). "The present data demonstrated that the expression of both Bim and PUMA were significantly higher in the tumor samples with GSTP1 GG-genotype than the samples with AA-genotype (p value 0.006 for Bim and 0.01 for PUMA)." (PMID 32265484, 2020). "Intriguingly, we found that the orthotopic implantation of GSTP1 knockdown cells in the pancreata of athymic nude mice resulted in drastically smaller tumors compared to scrambled controls in terms of both tumor weight and volume." (PMID 32526885, 2020). "At the conclusion of the experiment, we observed decreased tumor growth via abdominal ultrasounds in GSTP1 knockdown groups compared to the controls." (PMID 32526885, 2020). "In contrast, the level of 8-OHdG in tumor DNA was significantly higher in GSTP1 AA- than GG-genotypes (p value 0.012 in RAN samples; p value 0.014 in RAN + Tobacco samples)." (PMID 32265484, 2020). "Knockdown of either NQO1 or GSTP1 separately significantly decreased tumor volumes and weight, and combined knockdown resulted a much greater effect." (PMID 33087132, 2020). "Generally, data supported that GSTP1-1 activity contributes to the intrinsic drug resistance in this tumor." (PMID 31357662, 2019). "Highexpression of GSTP1 was observed in cell lines treated with chemotherapy drugs,pointing to the potential involvement of this protein in tumor resistance tochemotherapeutic treatments (Batist etal., 1986; Hayes andPulford, 1995; Huang etal., 2003)." (PMID 30816904, 2019).